AQP9 (aquaporin 9)
Diseases named in the same sentence as AQP9 in open-access papers (continued):
Sharing a sentence is not in itself a finding about the gene and the disease.
glioma (14 papers, 2010 to 2023). A benign or malignant brain and spinal cord tumor that arises from glial cells (astrocytes, oligodendrocytes, ependymal cells). "Since aquaporin 9 (AQP9) is closely linked to cellular-volume regulation, and is highly expressed in glioma, the effect of AQP9 expression on WK1 migration was investigated." (PMID 33637089, 2021). "The over-expression of AQP9 was observed across the whole surface of human glioma cells, associated with the energy metabolism, and counteracted the glioma-associated lactic acidosis by clearance of glycerol and lactate from the extracellular space." (PMID 25886458, 2015). "The increase of AQP9 expression may counteract the glioma-associated lactic acidosis by clearance of glycerol and lactate from the extracellular space and could be involved in the energy metabolism of the glioma." (PMID 21119878, 2010). "And AQP subtypes, including AQP1, AQP4 and AQP9, are overexpressed in glioma cells and correlated with tumor grade and malignancy." (PMID 34712604, 2021). "AQP1, AQP4 and AQP9 were reported to be related to angiogenesis, invasion and peritumoral edema in gliomas." (PMID 34712604, 2021). "High hazard ratios were noted for AQP5 and AQP9 in glioma and ovarian cancers; more research is needed on their possible pathophysiological roles." (PMID 32679804, 2020). "Upregulation of AQP1 and AQP4 protein and RNA has been the major focus of papers published in the glioma field, with additional work identifying possible involvement of AQP9." (PMID 32679804, 2020). "Studies have revealed that AQP9 was abundantly expressed in human glioma tissues, which is also correlated with the pathological grade of tumors." (PMID 31969493, 2020). "Glioma-associated DEGs CD244, IL21, RET, TGFA were up-regulated and AQP9, IGFBP2, EGFR, SOX9 were down-regulated specifically in the rat." (PMID 29352201, 2018). "In human glioma biopsies we detected a large number of AQP9+ cells either scattered throughout tumor parenchyma or in larger clusters that were assessed as immune cells based on cell size." (PMID 24086629, 2013). "Apparent AQP9+ glioma cells were frequently observed in proximity to blood vessels, where brain tumor stem cells have been observed previously." (PMID 24086629, 2013). "In a recent study AQP9 expression has been described in human glioma derived neurospheres, which suggested AQP9 expression in BTSCs." (PMID 24086629, 2013). "Our studies identify AQP9 expression in a limited population of glioma cells as well as in tumor infiltrating myelomonocytic cells." (PMID 24086629, 2013). "Nevertheless, in human glioblastoma most glioma cells throughout the tumour revealed a strong AQP9 expression across the whole surface of the cells." (PMID 21119878, 2010). "The epidermal growth factor receptor/extracellular signal-regulated kinase/p38/mitogen-activated protein kinase (EGFR/ERK/p38 MAPK) signaling pathway affects glioma proliferation and apoptosis, and AQP9 is involved in the oxidative phosphorylation pathway in glioma cells." (PMID 37280594, 2023). "However, upregulation of AQP9 was shown for glioma cells, and the expression levels were correlated to tumor severity." (PMID 35054513, 2022). "In human glioblastoma, AQP9 was strongly expressed in most glioma cell surfaces throughout the tumor, suggesting that AQP9 may represent a potential biomarker for this clinical condition." (PMID 35883453, 2022). "Increased expression of AQP9 has been observed in glioma tissue near vessels and might promote the invasion and motility of cells." (PMID 34712604, 2021). "In addition, we analyzed AQP9 mRNA expression in the glioma data set at the “The Cancer Genome Atlas Network” (TCGA,) website." (PMID 24086629, 2013). "In this study, we have examined microarrays to corroborate AQP9 mRNA expression in glioma." (PMID 24086629, 2013). "Interestingly, in several places AQP9 expressing glioma cells were localized in close proximity to blood vessels." (PMID 24086629, 2013).
glioma (continued). "Previous studies have suggested enhanced AQP9 expression in high-grade glioma." (PMID 24086629, 2013). "AQP9 expression may therefore require signals of the perivascular tumor environment or alternatively it may be restricted to a population of glioma stem cell early progenitor cells." (PMID 24086629, 2013). "AQP9 participates in the oxidative phosphorylation process of cellular mitochondria in glioma and can accelerate the clearance of metabolic wastes such as glycerol and lactic acid outside glioma cells, which is conducive to the rapid proliferation of glioma cells." (PMID 37280594, 2023). "However, whether AQP9 has a role in glioma cell volume regulation, migration, and mediating the migratory inhibition caused by Tf@pSiNPs has never been studied." (PMID 33637089, 2021). "Immunolabeling confirmed that within tumor regions, AQP9 was expressed in CD15+ and Calgranulin B+ leukocytes, but also in larger cells that morphologically resembled glioma cells." (PMID 24086629, 2013). "Although AQP9 was not involved in the inhibition of glioma cell migration mediated by Tf@pSiNPs, AQPs have been established as important mediators of cell volume regulation." (PMID 33637089, 2021). "AQP9 is not highly expressed in normal brain; however, increased levels observed in human glioma were correlated with pathological grade and are proposed to promote cell invasiveness via an AKT signaling pathway." (PMID 32679804, 2020). "AQP9 expressing glioma cells were negative for the brain tumor stem cell marker CD15, but were observed in proximity to CD15+ glioma cells." (PMID 24086629, 2013).
glioblastoma (13 papers, 2012 to 2026). The most malignant astrocytic tumor (WHO grade IV). "In glioblastomas, the expression of AQP9 mRNA is mainly caused by the infiltration of AQP9-expressing leukocytes into tumor sites." (PMID 34422053, 2021). "To obtain further evidence for enhanced AQP9 expression in glioblastoma and to understand a possible, underlying mechanism, we analyzed publicly available microarray data sets for correlation between AQP9 expression and other transcripts." (PMID 24086629, 2013). "It is postulated that the AQP9-mediated clearance of lactate and glycerol facilitates glioblastoma survival by counteracting the lactic acidosis which occurs during extensive hypoxia within glioblastoma tumors." (PMID 36765806, 2023). "In glioblastoma, lung and ovarian cancers, AQP9 also appeared to be a candidate of interest for cancer severity." (PMID 32679804, 2020). "In human glioblastoma, the most common and aggressive type of brain tumor, widespread and enhanced AQP9 expression, compared to normal brain, has been described." (PMID 24086629, 2013). "Expression of AQP9 in normal brain is limited, while widespread AQP9 expression has previously been reported in human glioblastoma." (PMID 24086629, 2013). "Out of 26 patients with elevated AQP9 expression (more than 2-fold above average), 18 patients were afflicted by mesenchymal glioblastoma." (PMID 24086629, 2013). "Here we describe a detailed immunolocalization of AQP9 in human glioblastoma, along with specific cellular markers." (PMID 24086629, 2013). "These analyses suggested that AQP9 mRNA expression in glioblastoma is primarily explained by tumor infiltration with AQP9 expressing leukocytes." (PMID 24086629, 2013). "A putative role of AQP9 in myelomonocytic cells in general as well as with regard to glioblastoma remains to be determined." (PMID 24086629, 2013). "Correlation of AQP9 mRNA expression with the mesenchymal type of glioblastoma therefore appears to result at least in part from the correlation of mesenchymal glioblastoma with inflammatory infiltrates." (PMID 24086629, 2013). "We also found that high levels of AQP9 mRNA expression were correlated with the mesenchymal type of glioblastoma." (PMID 24086629, 2013). "Similarly, AQP9 has been implicated in the progression of renal cell carcinoma and glioblastoma, and both AQP7 and AQP9 are highly expressed in ovarian cancer cells." (PMID 40927981, 2026). "They showed a significant increase in AQP9 mRNA expression in tumour stem cells, followed by high expression in differentiated cells, indicating that AQP9 may play a key role in glioblastoma carcinogenesis." (PMID 38336645, 2024). "We found that AQP9 expression differed significantly between glioblastoma types." (PMID 24086629, 2013). "To distinguish between these hypotheses we investigated the cellular expression of AQP9 in formalin fixed paraffin sections of 10 human tumor biopsies that were characterized as glioblastoma tissue by a pathologist." (PMID 24086629, 2013). "The aim in the current study was to verify AQP9 expression in glioblastoma." (PMID 24086629, 2013). "We found that AQP9 in glioblastoma tissue biopsies is expressed in a subset of malignant astrocytic cells and in tumor infiltrating CD15+ and Calgranulin B+ cells, thus identifying these cells as myelomonocytic linage cells, including neutrophils, eosinophils, and some monocytes, but not basophils." (PMID 24086629, 2013). "Furthermore, we wished to identify the cellular expression of AQP9 in glioblastoma tissue in co-labeling experiments with antibodies directed to specific cellular markers." (PMID 24086629, 2013). "We, therefore, propose that aquaporin 9 may have a central role in the tumorigenesis of glioblastoma." (PMID 22262958, 2012). "This implies a central role for aqp9 in the progenitor cell population in glioblastoma." (PMID 22262958, 2012).
glioblastoma (continued). "GBM responses to the AQP9 inhibitor would be interesting to test in classical and neural glioblastoma subtypes, which are not appreciably affected by dysregulation of Wnt/β-catenin." (PMID 34769339, 2021). "Permeability of AQP9 to lactate, glycerol, urea and hydrogen peroxide could facilitate glioblastoma survival by counteracting lactic acidosis that accompanies hypoxic conditions within glioblastoma tumors." (PMID 34769339, 2021). "Therefore, our microarray analyses suggested that previously observed, enhanced AQP9 mRNA and protein expression in glioblastoma may be explained by tumor infiltration with AQP9 expressing leukocytes." (PMID 24086629, 2013). "However, the specific cellular expression of AQP9 in glioblastoma remains unclear." (PMID 24086629, 2013). "In contrast to a previous study, we did not observe ubiquitous expression of AQP9 in glioblastoma biopsies." (PMID 24086629, 2013). "Furthermore this means that AQP9 expression in astrocytic glioma cells, as observed in 7 out of 10 evaluated patient biopsies, may not be correlated with the mesenchymal type of glioblastoma." (PMID 24086629, 2013).
Insulin resistance (12 papers, 2013 to 2024). Increased resistance towards insulin, that is, diminished effectiveness of insulin in reducing blood glucose levels. "Strikingly, the increased expression of AQP9 at the mRNA level has been linked to insulin deficiency or to insulin resistance in mice." (PMID 35457071, 2022). "In rodents, the expression of AQP9 is negatively regulated by insulin at the transcriptional level, explaining why hepatic AQP9 is enhanced in situations of insulin resistance." (PMID 39596202, 2024). "Obese‐ and insulin‐resistant mice show increased aqp7 and aqp9 expression, in spite of hyperglycemia." (PMID 35075822, 2022). "In rodents, the expression of hepatocyte AQP9 is negatively regulated by insulin at the transcriptional level, likely explaining why hepatic AQP9 is increased in conditions of insulin resistance." (PMID 35883453, 2022). "Interestingly, although hepatic AQP9 protein level was similar in obese male and female patients, the lower glycerol permeability detected in obese women hepatocytes might suggest a decreased risk of developing insulin resistance and NAFLD." (PMID 35187089, 2022). "In rodents, insulin downregulates hepatocyte Aqp9 gene transcription by acting on an insulin response element (IRE), which is consistent with AQP9 augmentations observed in animal models of insulin resistance." (PMID 27409609, 2016). "In rodents, hepatic AQP9 is repressed transcriptionally by insulin whereas AQP9 increases in states of insulin resistance." (PMID 24205128, 2013). "In rodents, the negative regulation of Aqp9 transcription by insulin may account for enhanced hepatic AQP9 expression in insulin resistance." (PMID 37681902, 2023). "In spite of showing similar hepatic AQP9 protein, women exhibit lower hepatocyte glycerol permeability than men, which might contribute to their lower prevalence of insulin resistance and NAFLD." (PMID 26594198, 2015). "Qutanhuoxue decoction may improve insulin resistance by restoring the expression of aqp7 and aqp9." (PMID 31275413, 2019). "Recently, hepatic AQP9 was found downregulated in obese patients with NAFLD and steatohepatitis (NASH), with even lower levels in patients with insulin-resistance, suggesting a compensatory mechanism to prevent glycerol availability for triglycerides accumulation and hepatic gluconeogenesis." (PMID 35187089, 2022).
liver cancer (12 papers, 2015 to 2025). An epithelial or non-epithelial malignant neoplasm that arises from the liver. "CD133+ liver cancer stem cells (LCSCs) show deficient AQP9 expression." (PMID 35883453, 2022). "To confirm the function of AQP9 in arsenic uptake, we used liver cancer cell lines as in vitro models." (PMID 35967171, 2022). "Arsenic-sensitive liver cancer cell line (HepG2) and arsenic-resistant HepG2 (AsHepG2) cells are employed to study the role of aquaporin 9 (AQP9) in arsenic uptake and tolerance." (PMID 35967171, 2022). "AQP9 can also mediate intracellular arsenic accumulation and arsenic hypersensitivity in leukemia cell line K562, human lung cancer cells, liver cancer cell line (HepG2), and primary mouse hepatocytes." (PMID 35967171, 2022). "Dramatic increases in patient risk were observed for AQP3 in esophageal cancer (HR18.4), and AQP9 in liver cancer (HR 10.8)." (PMID 32679804, 2020). "Deceased AQP9 expression in HCCs can increase resistance of hepatic cancer cells to apoptotic stimulation." (PMID 25886458, 2015). "This highlights AQP9 as a promising target for immunotherapy in liver cancer." (PMID 39796114, 2024). "Meta-analyses confirmed predominantly negative associations between AQP protein and RNA expression levels and patient survival times, most notably for AQP1 in lung, breast and prostate cancers; AQP3 in esophageal, liver and breast cancers; and AQP9 in liver cancer." (PMID 32679804, 2020). "Taken all together, as Wnt/β-catenin signaling plays key roles in the pathogenesis of liver cancer, AQP9 could affect the proliferation, invasion, migration and apoptosis of HCC cells through Wnt/β-catenin pathway." (PMID 31969493, 2020). "Few studies have been performed regarding the role of AQP9 in liver cancer." (PMID 27329843, 2016). "Therefore, the purpose of the present study was to investigate AQP9 expression and function in liver cancer." (PMID 27329843, 2016). "Here we report AQP9 expression and function in liver cancer." (PMID 27329843, 2016). "Moreover, AQP9 was shown to be critical in tumor immunity in liver cancer." (PMID 35883453, 2022). "Moreover, AQP9 participates in hepatic glycerol metabolism reprogramming in early rat liver cancer." (PMID 35972604, 2022). "However, few studies have investigated the role of AQP9 in liver cancer." (PMID 27329843, 2016). "In this study, the author proved that AQP9 mediated by insulin-like growth factor 2 (IGF2), inhibited liver cancer stem cell stemness through ROS/β-catenin/FOXO3a." (PMID 35972604, 2022). "Furthermore, aquaporin 9 (AQP9), known to inhibit liver cancer growth and metastasis, and cadherin-related family member 5 (CDHR5), which suppresses HCC cell proliferation, were up-regulated in the Matrigel group." (PMID 40852642, 2025). "Hepatic cancer expresses similar types of AQPs with colon cancer, e.g. AQP1, AQP3, AQP5, and AQP9." (PMID 25886458, 2015). "The study also found an upregulation of AQP9 and a downregulation of AQP3 (two molecules belonging to the same family of AQP7), indicating that the dysregulation of the aquaporine activity could play a fundamental role in the liver cancer development and progression." (PMID 31757200, 2019). "At present, there had been many reports detailing the role of AQP9 in liver cancer, renal cell carcinoma, and NAFLD, but no reports had been found on the pathogenesis of AQP9 in the comorbidity of IBD and psoriasis." (PMID 40093802, 2025).
systemic inflammatory response syndrome (12 papers, 2018 to 2024). SIRS is a serious condition related to systemic inflammation, organ dysfunction, and organ failure. "AQP9 is also augmented in activated polymorphonuclear leukocytes in patients with systemic inflammatory response syndrome and infective endocarditis." (PMID 33673336, 2021). "AQP9 has been reported to be upregulated in patients with systemic inflammatory response syndrome compared to healthy individuals, and this is attributed to the functional impact of AQP9 on F-actin polymerization, leading to changes in the morphology and function of neutrophils." (PMID 37325483, 2023). "However, previous studies report that AQP9 is involved in inflammatory diseases such as ulcerative colitis, systemic inflammatory response syndrome, and rheumatoid and osteoarthritis." (PMID 36059464, 2022). "AQP9 expression in neutrophils may play a role in establishing contact hypersitivity and is enhanced in systemic inflammatory response syndrome." (PMID 30300410, 2018). "AQP9, in particular, demonstrates augmented expression in activated polymorphonuclear leukocytes during systemic inflammatory response syndrome (SIRS) and infective endocarditis." (PMID 39544938, 2024). "AQP9 expression is also elevated in activated polymorphonuclear leukocytes in patients suffering from systemic inflammatory response syndrome (SIRS) and infective endocarditis." (PMID 37762642, 2023). "Patients with systemic inflammatory response syndrome (SIRS) show increased AQP9 expression in neutrophils compared to healthy controls." (PMID 36237611, 2022). "A function of AQP9 in F-actin polymerization influencing both morphologic and functional (i.e., cell migration) changes of neutrophils has also been suggested to explain its increased expression in patients with systemic inflammatory response syndrome compared to healthy subjects." (PMID 35883453, 2022). "The AQP9 expression level also augmented in activated polymorphonuclear leukocytes in subjects with systemic inflammatory response syndrome (SIRS) and infective endocarditis." (PMID 35883453, 2022). "Patients with systemic inflammatory response syndrome (SIRS) have enhanced AQP9 expression in activated polymorphonuclear leukocytes as compared to healthy control subjects." (PMID 33670755, 2021). "The overexpression of AQP9 is also connected with systemic inflammatory response syndrome (SIRS)." (PMID 38674035, 2024). "In addition, patients with systemic inflammatory response syndrome (SIRS) show increased AQP9 expression in neutrophils compared to healthy controls." (PMID 29449936, 2018).